CD4 (CD4 molecule)
Diseases named in the same sentence as CD4 in open-access papers (continued):
Sharing a sentence is not in itself a finding about the gene and the disease.
pneumonia (continued). "The onset of acute pneumonia induced immune differentiation of CD4+T cells in the spleen of mice, accompanied by an increase in Th17 cell ratio and a decrease in Treg cell ratio, as well as a severe decrease in Treg/Th17 cell ratio." (PMID 35782123, 2022). "Taken together, these results suggest that SSTI primes enhanced inflammation in the lungs early after secondary pneumonia and that neutralization of Hla enabled expansion of CD4+ T cell populations." (PMID 35983063, 2022). "Despite this limitation, this study is the first to reveal systemic perturbations of the microbiota and the relationship between respiratory microbiota composition and CD4 status in HIV-positive patients with pneumonia." (PMID 35814692, 2022). "With respect to the possible pneumonia pathogens, Anelloviridae were more commonly identified in patients with a CD4 count of less than 200 cells per mL than in patients with a CD4 count of 200 cells per mL or greater (Fisher’s exact test p=0·036)." (PMID 35544096, 2022). "Further, CD4+CD25+ T cells from pneumonia patients have been found to secrete significantly lower levels of cytolytic molecules than those from healthy individuals and to also have poor capacity to suppress effector T cell proliferation." (PMID 34257746, 2021). "In mice, DNA methylation of the promoters of CD4+ T cell-related genes were found to contribute to poor immune responses of neonates during pneumonia." (PMID 34444938, 2021). "At the late time point, a similar trend was observed for the CD4+ T-cell proliferative response particularly in pneumonia patients." (PMID 34835067, 2021). "Another interesting finding was that the pneumonia severity index in elderly patients was inversely correlated with the proportion of Foxp3+ and Helios+ cells among CD4+ T cells and the level of TGF-β." (PMID 34257746, 2021). "We found the exhaustion of CD4+ TEM in patients with acute pneumonia accompanied with a decrease of CCR7+CD45RA+ naïve T cells (CD38+HLA‐DR+)." (PMID 34841705, 2021). "Compared to the mild/moderate cases, patients with severe pneumonia had an increased count of CD8+ lymphocyte with a decreased CD4+ lymphocyte count." (PMID 33937149, 2021). "Pneumocystis jirovecii is another opportunistic fungus that causes pneumonia, particularly in HIV-positive patients, with an inverse relationship between the CD4+ T cell count in the blood and the risk of infection by P. jirovecii." (PMID 34557097, 2021). "Colonisation induces antibody and CD4+ Th17 responses to protein antigens and antibody to capsular antigen, preventing recolonisation of the nasopharynx, pneumonia and sepsis." (PMID 33804077, 2021). "At the early time point, rapid CD4+ T-cell response was higher in patients with pneumonia, while the CD8+ T-cell response was poor in all patients." (PMID 34835067, 2021). "In elderly pneumonia patients, CD4+ T cells from peripheral blood mononuclear cells exhibit reduced Foxp3 and Helios expression in comparison with age- and sex-matched healthy controls." (PMID 34257746, 2021). "The proportion and frequency of CD4+ T cells were significantly decreased while that of CD8+ T cells were significantly increased in patients with acute pneumonia." (PMID 34841705, 2021). "Only in IC patients at the early time point did we observe a significant difference between patients with pneumonia or mild symptoms in proliferative CD4+ and CD8+ T-cell responses (p < 0.001)." (PMID 34835067, 2021). "Reduces levels of B lymphocytes, CD8+ proportion, IL-1α, IL-1β, IL-2, IgM, IgG, etc., reduces quality of thymus, spleen and lung of pneumonia mice, and increase CD4+/CD8+ and NK cell proportion." (PMID 32848729, 2020). "This 41 year-old HIV-HCV coinfected patient with a high CD4 count who received sofosbuvir/ledipasvir died from (TB-negative) pneumonia several weeks after treatment completion." (PMID 33326423, 2020).
pneumonia (continued). "The authors also showed increased levels of IL-17A and CD4+ cells in lungs of previously colonized mice, indicating a potential role for T cell mediated immunity for prevention of pneumonia." (PMID 30881363, 2019). "Interferon gamma (IFN-γ), an important cytokine in the host defense against infection, which is derived mainly from NK and CD4+ T cells during pneumonia." (PMID 31447768, 2019). "The mechanisms involved in preventing infection depends on anatomical site, with an emphasis on antibody during systemic infection and on Th17 CD4+ cells for mucosal infection, with pneumonia seemingly a combination of the two." (PMID 30881363, 2019). "Despite these limitations, this study is the first to reveal a systemic microbiota perturbation in HIV-infected pneumonia patients and a relationship between gut microbiota composition and CD4 status." (PMID 30857553, 2019). "Two additional papers have also demonstrated an important role for Th17 CD4+ cells induced by prior exposure to S. pneumoniae for protection against subsequent severe S. pneumoniae pneumonia." (PMID 30881363, 2019). "Conversely, CD26 expression in the lung of active TB patients was significantly higher than that found in pneumonia, at least in the CD4+ cell subset." (PMID 30026741, 2018). "The incidence of pneumonia is increased with smoking and treatment interruption and is directly dependent on viral load in patients when adjusted for CD4 counts." (PMID 29789655, 2018). "CD4+ T-helper 17 (Th17) cells and Interleukin (IL)-17A play an important role in clearing pathogens in mouse models of pneumonia." (PMID 28806403, 2017). "Since this condition can present with minimal symptoms in patients with low CD4 cell counts, pneumonia is more likely to be misdiagnosed." (PMID 25972115, 2016). "In lavage from patients with pneumonia, IL-22 concentrations were unrelated to total percentages of lymphocytes, macrophages, neutrophils, eosinophils and to the CD4 to CD8 T cell ratio (p = 0.5, 0.98, 0.86, 0.98, 0.65, respectively)." (PMID 27388918, 2016). "Only one study describes the phenomenon in humans; elevated IAV-specific CD8+ and CD4+ T cell responses were found in pandemic 2009 H1N1-infected children with severe pneumonia." (PMID 26029218, 2015). "A three-year-old HIV-infected child with severe immunosuppression (CD4+ T-cell count 12 × 106/L) was admitted to hospital with pneumonia, gastroenteritis and herpes gingivostomatitis." (PMID 29568581, 2015). "Three studies reported data for bacterial pneumonia, but none allowed a quantitative summary of the effect estimates of smoking on pneumonia by CD4 count category." (PMID 23339513, 2013). "CD4 depletion (>90% efficacy) abolished the colonisation-induced enhancement of BALF IL-17 levels at 18 hours in response to S. pneumoniae pneumonia in previously colonised mice." (PMID 22003400, 2011). "This is accompanied by an increased frequency of CD4+IFNγ+ effector T-cells which cannot prevent lethal pneumonia." (PMID 22096480, 2011). "Vaccination of MyD88-deficient mice with M. bovis BCG induced IFNγ-producing CD4+ T-cells in vivo, but the TH1 cells only partially prevented lethal pneumonia upon challenge with M. tuberculosis." (PMID 22096480, 2011). "We found that HAART use improved the prognosis after a pneumonia-related hospitalization also after adjusting for CD4+ cell count, which is in line with results from earlier studies." (PMID 19750011, 2009). "No characteristics were significantly associated with FEV1 including age, gender, race/ethnicity, HIV risk factor, smoking or pack-year history, CD4 cell count or HIV viral level, use of HAART, or history of pneumonia." (PMID 19621086, 2009). "Other pre-HAART era risk factors for respiratory symptoms included intravenous drug use (IDU), low CD4 cell count, and previous pneumonia." (PMID 19621086, 2009).
pneumonia (continued). "At the time of the pneumonia event the median CD4 cell count was 193 cells/mm3 (IQR: 35, 424) among patients with bacterial pneumonias and 35 cells/mm3 (IQR: 13, 118) among patients with PCP (P-value < 0.001)." (PMID 19340321, 2008). "No prior antiretroviral therapy use (P-value <0.001), higher HIV RNA level (P-value = 0.01), lower CD4 count (P-value = 0.01), younger age (P-value = 0.01), and alcohol use (P-value = 0.04) were independent predictors of pneumonia." (PMID 19340321, 2008). "The application of r-hGH in severe neurosurgical patients was effective in increasing the number of CD4+ T cells, down-regulating inflammatory mediators, shortening the cure time of pneumonia, intracranial infections and urinary tract infections, and improving patients’ prognosis." (PMID 39792837, 2025). "This study aimed to use CD4+ T cells count as an objective parameter to systematically characterize the evolution of the pathogen profile in bronchoalveolar lavage fluid-targeted next-generation sequencing (BALF-tNGS) from patients with severe pneumonia." (PMID 41488483, 2025). "Furthermore, 291 common and 14 hub genes were associated with pneumonia and various unique immune cell signatures across DEG categories were associated with neutrophils, monocytes, and CD4 memory effector T cells." (PMID 39205185, 2024). "In the colistin-resistant pneumonia model, treatment with a single dose of memory B or CD4+ T cells also reduced the bacterial load in the lungs compared with the tigecycline and sulbactam groups and was better than the tigecycline group in terms of blood clearance." (PMID 39408879, 2024). "Similarly, a recent study about elderly patients with pneumonia showed that lower levels of CD4+ T cells were observed in the early deceased group than the late deceased patients or survivors." (PMID 37773700, 2023). "The CD3+, CD4+, and CD4+/CD8+ ratio values were higher than the severe HAdV pneumonia group." (PMID 36732702, 2023). "Likewise, THC treatment of legionella–pneumonia-loaded DCs leads to the poor stimulation of culture-primed splenic CD4 T cells." (PMID 35214123, 2022). "Bacteria associated with chronic non-progressive pneumonia in sheep and goats (M. ovipneumoniae) induce polyclonal suppression of CD4+, CD8+, and B lymphocyte subsets in vitro." (PMID 35630474, 2022). "Indeed, protective immunity was associated with higher levels of inflammatory gene transcripts and adoptive transfer of Hla-specific anti-serum resulted in more CD4+ T cells in the lung and protection against lethal pneumonia." (PMID 35983063, 2022). "In addition, patients with pneumonia developed higher memory CD4+ and CD8+ T-cell responses than patients with mild symptoms." (PMID 35744768, 2022). "Reduction in CD4 and CD8 T cells were associated with severe pneumonia." (PMID 33602949, 2021). "Of subsets of CD3+ T cells, the frequencies of cluster 06 identified as NKT cell with markers of CD3+ CD3+CD56+CD8a+TCRab+CD45RA+CCR7−CD45RO+Tbet+GranzymeB+ and cluster 12 as CD4+ TCM with markers of CD3+CD4+TCRab+CD45RA−CCR7+CD45RO+CD27+CD127+ significantly decreased in acute pneumonia." (PMID 34841705, 2021). "The expression levels of CD40L, Eomes and Granzyme B were significantly higher in patients with acute pneumonia, which indicates that the differentiation promotion of CD4+ T cells into Th17 and IgE secretion might be inhibited." (PMID 34841705, 2021). "In HIV-infected children, Rhinovirus has been shown highly prevalent, during both pneumonia and bronchiolitis, but without data regarding a putative association with the level of CD4 T-cell deficiency." (PMID 32953200, 2020). "Thus, vitamin A supplement after neonatal S. pneumoniae pneumonia altered the productions of lung CD4+T cells during AAD." (PMID 32144294, 2020).
pneumonia (continued). "Secondly, by knowing the mechanisms required for preventing specific diseases such as pneumonia these could be targeted by novel vaccines, for example by aiming to induce CD4+ cellular (mainly Th17) mediated immunity." (PMID 30881363, 2019). "We further theorized that gut microbiota composition of HIV-infected pneumonia patients is related to peripheral CD4 cell count and that the products of the gut microbiome influence the behavior of immune cell populations crucial to control of microbial infection." (PMID 30857553, 2019). "Moreover, patients with active TB showed a significantly lower expression of CXCR3 in the lung compared to patients with pneumonia in both CD4+ and CD8+ cell subsets." (PMID 30026741, 2018). "Moreover, the incidence of pneumonia is increased with smoking and is directly dependent on viral load in patients when adjusted for CD4 counts, suggesting that viral replication also plays an important role in lung infections." (PMID 29789655, 2018). "If the results regarding the association between CD4 count and bacterial infections were expected, although rarely described, the independent association between HIV RNA replication with the risk of occurrence of SBI and pneumonia remains difficult to explain." (PMID 27050752, 2016). "In addition, Pneumocystis (carinii) jiroveci pneumonia prophylaxis was previously recommended in patients with CD4 >200 cells/μL combined with anergy." (PMID 24499779, 2014). "It is clear then that CD4 count is critical and this reinforces our conclusion that smoking is not an important risk factor for this pneumonia." (PMID 23339513, 2013). "One patient with postmortem pneumonia presented with diarrhea and a CD4 cell count of 1 cell/mm3." (PMID 22432042, 2012). "In HIV-infected patients with a CD4 cell count below 50/mm3 without an identified cause of pneumonia, systematic AFB direct sputum examination is justified because of atypical clinical features (without cavitation) and high pulmonary mycobacterial burden." (PMID 21731675, 2011). "In a large survey of an HIV-infected cohort in the United States, a protective effect of PPV-23 vaccination was also shown against all-cause pneumonia, and this benefit was lost in patients with VL >100,000 copies/mL, irrespective of the CD4 count." (PMID 22194853, 2011). "We have shown that CCL5 inhibition resulted in lower IFN-γ-secreting CD4+ T cells and significantly more PspA-specific IL-10-producing CD4+ T cells, which corresponded with the transition from pneumococcal carriage to lethal pneumonia." (PMID 20195541, 2010). "For the second aim, a number of patient characteristics were predictive of developing pneumonia in bivariate analyses, including smoking, African American race, younger age, alcohol use, crack cocaine use, antiretroviral use, a lower CD4 cell count and higher HIV RNA level." (PMID 19340321, 2008). "Nineteen women (28%) progressed to a CD4 count <200 cells/μL, and twelve women (18%) died during follow-up: 1 with pneumonia, 1 with fever, 1 with hematemesis and abdominal distention, and 9 of unknown causes." (PMID 17594484, 2007). "Specifically, pneumonia patients exhibited elevated proportions of Macrophages M0, Monocytes, Neutrophils, and regulatory T cells (Tregs) in peripheral blood, alongside reduced proportions of resting NK cells, activated CD4 memory T cells, resting CD4 memory T cells, and CD8 T cells." (PMID 41300746, 2025). "Moreover, in another study of a pneumonia model in rats, the recipients of purified T cells, or CD4+ T cells, from rats previously challenged with P. aeruginosa exhibited improved clearance of bacterial load from the airways compared with recipients of cells from unimmunized donors." (PMID 39408879, 2024).
pneumonia (continued). "Thus, a vaccine that aims to protect against localised invasive S. aureus infections in the heart (i.e., endocarditis) bone (i.e., osteomyelitis), or lung (i.e., pneumonia) should aim to boost bacterium specific CD4+ Th1 polarised Trm in these tissue compartments." (PMID 35637249, 2022). "The magnitude of increase in CD4+ T cell subsets in the mediastinal LNs following pneumonia was consistently larger than the increase in inguinal LNs following SSTI, suggesting that, contrary to our hypothesis, pneumonia effectively expands local effector T cells." (PMID 35983063, 2022). "Other limitations of this study include only assessing antibody responses to 254 protein antigens which is likely to have missed important antibody responses and lack of data on CD4 cellular responses or on protection against pneumonia caused by a heterologous strain." (PMID 33804077, 2021). "Moreover, we found that the exhausted CD4+ T subsets exist in acute pneumonia and stable pneumonia." (PMID 34841705, 2021). "Fortunately, the CD4+ T cell count of our case was normal from 2016 to now, which might be the reason for not causing severe pneumonia." (PMID 32703286, 2020). "Hence the human data has identified local pulmonary Th17 CD4+ and antibody specific for S. pneumoniae that are boosted by nasopharyngeal colonization which could potentially assist lung immunity to pneumonia as has been described in mouse models." (PMID 30881363, 2019). "Thus, specific gut microbiota taxonomic perturbations associated with CD4 status are consistent irrespective of pneumonia or antiretroviral treatment status in HIV-infected patient populations." (PMID 30857553, 2019). "Thus, our data indicates that variation in HIV–pneumonia associated lower airway bacterial community is neither related to CD4 count nor to the degree of similarity with gut microbiota composition." (PMID 30857553, 2019). "Although unmeasured confounding factors cannot be ruled out as a contributory cause of the increased long term risk of death, pneumonia could also be viewed as a marker of immune system frailty that may not be reflected by the CD4+ cell count." (PMID 19750011, 2009). "Primary prophylaxis of Pneumocystis jirovecii pneumonia (PCP) in people with HIV (PWH) and CD4+ counts <200 cells/μL using trimethoprim/sulfamethoxazole (TMP-SMX) is highly effective but often poorly tolerated." (PMID 41893121, 2026). "Information on the distribution of CD4+ T cell counts in the HIV group and the HIV with pneumonia group is of great relevance, as it provides insights into the immune function of patients in each category." (PMID 38251391, 2024). "Pneumocystis jirovecii pneumonia (PCP) is a rare, life-threatening opportunistic fungal infection that rarely occurs with CD4 counts greater than 200 cells/mm3." (PMID 37942381, 2023). "Using this approach, we found significantly more LkT/C+ CD44+ CD4+ T cells in mice that recovered from SSTI, compared with those that recovered from pneumonia, thus confirming that only SSTI elicited S. aureus-specific memory CD4+ T cells." (PMID 35983063, 2022). "We further analyzed the receiver operating characteristic (ROC) curve to analyze the accuracy of the counts of CD3+, CD4+, and CD8+ T-cells for use as a biomarker of pneumonia in Adv+ patients." (PMID 36161612, 2022). "When we divided the patients according to T and B cell subsets, we found that pneumonia was statistically more frequent in patients with low CD3+ (16/39, 41% vs 2/24, 8.3%, P = 0.0085) and CD4+ (17/43, 39.5% vs 1/18, 5.5%, P = 0.012) T cells." (PMID 35257272, 2022). "It has a therapeutic impact on pneumonia model rats by reducing B lymphocytes, CD8+ ratio, and elevated levels of IL-1α, IL-1β, IL-2, IL-10, TNF-α, IFN-α, IFN-γ, IgM, IgG, CD4+/CD8+, and NK cells." (PMID 36388945, 2022).